MTMR2 (myotubularin related protein 2)
Diseases named in the same sentence as MTMR2 in open-access papers:
MTMR2 is named in the same sentence as 45 diseases in open-access papers, as found by Europe PMC text mining. Sharing a sentence is not in itself a finding about the gene and the disease. The quoted sentences say what the papers report.
neuropathy (15 papers, 2008 to 2025). A disorder affecting the nervous system that manifests with pain, tingling, numbness, and/or muscle weakness. "We first demonstrated that this neuropathy is caused by loss of the MTMR2 phospholipid phosphatase and generated a faithful mouse model for the disease, the Mtmr2−/− mouse." (PMID 27799291, 2016). "Mice with a recessive mutation in Mtmr2 exhibit peripheral neuropathy, and aspects of this neuropathy are reversed in the setting of Fig4 haploinsufficiency." (PMID 24004519, 2013). "We have generated a Mtmr2-null mouse which models the CMT4B1 neuropathy and we reported that loss of Mtmr2 specifically in Schwann cells is both sufficient and necessary to provoke myelin outfoldings." (PMID 22028665, 2011). "At this stage, sciatic nerves from Mtmr2−/−Fig4−/− double null mice were more severely hypomyelinated than Mtmr2+/+Fig4−/− mice with a higher g-ratio, demonstrating that Mtmr2 loss exacerbates the neuropathy of Mtmr2+/+Fig4−/− mice." (PMID 22028665, 2011). "We previously reported that autosomal recessive demyelinating Charcot-Marie-Tooth (CMT) type 4B1 neuropathy with myelin outfoldings is caused by loss of MTMR2 (Myotubularin-related 2) in humans, and we created a faithful mouse model of the disease." (PMID 22028665, 2011). "Finally, it should be noted that several genes identified in our screening have been associated with neuropathies or myopathies (Charcot–Marie–Tooth syndrome [MTMR2]; Dyggve–Melchior–Clausen syndrome [DYM])." (PMID 36661306, 2023). "In addition, we found that haploinsufficiency of Fig4 does not ameliorate effects of Mtm1 mutation in muscle, in contrast to a previous report that haploinsufficiency of Fig4 rescues the neuropathy associated with Mtmr2 mutation." (PMID 24004519, 2013). "Knockout mice for the gene MTMR2 demonstrate progressive neuropathy and depleted spermatids and spermatocytes." (PMID 33250925, 2020). "Mutations in MTMR2 and MTMR13 (also called SET-binding factor 2) cause the demyelinating CMT4B1 and CMT4B2 neuropathies respectively with early-onset glaucoma." (PMID 28553203, 2017). "Mtmr2 as well as Mtmr13 knockout mice exhibit a progressive neuropathy that becomes evident much later in the life span of these mice (∼6 months)." (PMID 23818870, 2013). "On the basis of the ability of reduced FIG4 levels to rescue aspects of Mtmr2-dependent neuropathy, we evaluated the effect of Fig4 haploinsufficiency on the myopathy of Mtm1-knockout mice." (PMID 24004519, 2013). "We first demonstrated that loss of function mutations in the MTMR2 (Myotubularin-related 2) gene cause autosomal recessive demyelinating Charcot-Marie-Tooth type 4B1 (CMT4B1, OMIM #601382) neuropathy with myelin outfoldings." (PMID 22028665, 2011). "Mutations in some phosphoinositide metabolism genes (FIG4, PTEN, MTMR2, and SBF1) also cause neuropathies with conduction slowing and/or CB,26, 27, 28 suggesting a more fundamental role of GPI in the pathophysiology of this inherited neuropathy, independent of the GPI‐APs that are affected." (PMID 39444079, 2025). "Whereas Fig4 haploinsufficiency improves the neuropathy phenotype of Mtmr2 KO mice, Mtmr2 mutation does not appear to positively modulate the Fig4 phenotype (and in fact increases motor neuron loss)." (PMID 31413155, 2019). "Particularly, we feel that laryngeal involvement might be a relevant and initial finding inearly-onset CMT4B1 neuropathy and thus all the patients with positive molecular genetics for MTMR2 should be promptly investigated for laryngeal function." (PMID 28190646, 2017). "Mtmr2 knockout mouse models develop a mild CMT4B1-like neuropathy and azoospermia." (PMID 18429927, 2008). "Interestingly mutations in the coupled active and dead phosphatases, MTMR2 and MTMR13, lead to very similar neuropathies, distinguished only by the age of onset and the major involvement of proximal muscles in CMT4B1, often resulting in a more severe neuropathy." (PMID 22496665, 2012).
neuropathy (continued). "Our data suggest that niacin treatment partially ameliorates the CMT4B1 neuropathy without interfering with nerve regeneration, which we found to be altered in Mtmr2 KO mice." (PMID 39926607, 2025). "Unlike its interaction partners MTMR13 or MTMR2 (bound to Rab35 via MTMR13 or MTMR5) Rab35 does not appear to be an inherited neuropathy disease gene." (PMID 32503983, 2020). "Conversely, conditional deletion of Mtmr2 in motoneurons, with the HB9 transgene, did not result in any overt phenotype suggesting that loss of Mtmr2 in Schwann cells, but not in motor neurons, is both sufficient and necessary to cause CMT4B1 neuropathy." (PMID 34573256, 2021). "However, in contrast to our findings in Mtm1-null mice, Bolino and colleagues found that plt haploinsufficiency rescued neuropathy in Mtmr2-knockout animals." (PMID 24004519, 2013). "Autophagy has not yet been studied in the context of CMT4B causing mutations in MTMRs but the roles of both MTMR2 and MTMR13 in autophagy and their functional association with each other presents autophagy impairment as a possible common pathomechanism in mutant MTMRs leading to neuropathy." (PMID 28553203, 2017).
Charcot-Marie-Tooth disease (6 papers, 2010 to 2024). An inherited degenerative disorder involving the peripheral nerves. "Mutations in either MTMR13 or MTMR2 are causally linked to human Type 4B Charcot-Marie-Tooth disease, an inherited disorder of the peripheral nervous system with abnormal nerve myelination." (PMID 38829202, 2024). "Functional evidence for in vivo significance of these interactions comes from genetic studies in humans that show that mutations of either the catalytically active MTMR2 or its catalytically inactive binding partner MTMR13 result in similar forms of Charcot-Marie-Tooth disease." (PMID 23818870, 2013). "Clinical phenotype of patients with MTMR2 related Charcot-Marie-Tooth disease." (PMID 31680794, 2019). "Additionally, mutations in myotubularin-related protein 2 (MTMR2) and MTMR13 cause Charcot-Marie-Tooth Disease." (PMID 27018598, 2016). "Mutations in genes encoding MTMR2 and MTMR13 have both been associated with Charcot-Marie-Tooth (CMT) disease raising the possibility that MTMR12 deficiency may result in neurological defects such as those seen in CMT." (PMID 23818870, 2013).
gastric cancer (6 papers, 2019 to 2024). A primary or metastatic malignant neoplasm involving the stomach. "The present study aimed to investigate the roles and clinical relevance of MTMR2 as well as the underlying mechanisms in gastric cancer (GC)." (PMID 31113461, 2019). "MTMR2 promotes invasion and metastasis of gastric cancer via inactivating IFNγ/STAT1 signaling and modulates TIME by promoting the progression of NK/T cell lymphoma by targeting JAK1." (PMID 39408697, 2024). "MTMR2 an essential promoter in gastric cancer invasion and metastasis by inactivating IFNA1/STAT1 signalling and acts as a new prognostic indicator and a potential therapeutic target for gastric cancer." (PMID 35057823, 2022). "For example, the phosphatase Myotubularin-related protein 2 (MTMR2) promotes invasion and metastasis in gastric cancer by inactivating IFNγ/STAT1 signaling pathway." (PMID 34638338, 2021). "MTMR2 (myotubularin-related protein-2) is shown to inactivate IFN γ/STAT signaling and promote gastric cancer (GC) invasion and metastasis and maybe a new therapeutic target for the treatment of GC." (PMID 32992741, 2020).
glaucoma (5 papers, 2008 to 2023). Increased pressure in the eyeball due to obstruction of the outflow of aqueous humor. "In addition, the MTMR2 and MTMR13 complex is also impacted in glaucoma and cancer, and both MTMR2 and MTMR13 are referred to as disease-causing proteins." (PMID 34203203, 2021). "CMT4B1 (MIM 601382) is caused by mutations in the myotubularin family member MTMR2, whereas CMT4B2 (MIM 604563), which can also feature glaucoma, is caused by mutations in MTMR13 (SBF2), which encodes a phosphatase-dead myotubularin-related protein that interacts directly with MTMR2." (PMID 31413155, 2019). "Mutations in the MTMR13/SBF2 gene, which encodes a catalytically inactive member of the myotubularin family involved in heterodimerization with MTMR2, cause CMT4B2 (OMIM 604563), which has similar pathological features to CMT4B1, with additional glaucoma in some patients." (PMID 18429927, 2008).
myotubular myopathy (5 papers, 2009 to 2024). "This implies that increasing the expression of either MTMR1 or MTMR2 in patient muscle is a viable potential treatment strategy for myotubular myopathy." (PMID 19197364, 2009).
Charcot-Marie-Tooth disease type 4B (4 papers, 2019 to 2025). "Inactivating mutations in MTMR2 are found in Charcot-Marie-Tooth disease type 4B1, a severe autosomal recessive neuropathy with demyelination and myelin outfoldings of the nerve." (PMID 38328115, 2025). "Mutations in MTMR2 cause Charcot-Marie-Tooth disease type 4B, which features a generalized loss of large myelinated nerve fibers and focally folded myelin sheaths giving rise to inadequate nerve signaling to muscles, resulting in muscle weakness and atrophy." (PMID 34450027, 2021). "Overview of MTMR2 related Charcot-Marie-Tooth disease type 4B1." (PMID 31680794, 2019). "Thus, in addition to disrupted endosomal trafficking by MTMR2 inactivation, it is plausible that the reduced PM levels of PtdSer and PI4P further contributes to the demyelination observed in Charcot-Marie-Tooth disease type 4B1." (PMID 38328115, 2025).
Vocal cord paralysis (3 papers, 2017 to 2025). A loss of the ability to move the vocal folds. "We here report the case of a patient with a novel mutation in the MTMR2 gene, who started to experience stridor and was diagnosed with bilateral vocal cord paralysis at the age of 18 months." (PMID 28190646, 2017). "Other significant clinical clues in demyelinating CMT subtypes included vocal cord paralysis in GDAP1, ophtalmoparesis and tongue fasciculations in FGD4, severe sensory ataxia in PRX, respiratory involvement in MTMR2 and SBF2, similar to previous reports." (PMID 39776111, 2025).
X-linked myotubular myopathy (3 papers, 2008 to 2012). A rare X-linked congenital myopathy characterized by numerous centrally placed nuclei on muscle biopsy and that presents at birth with marked weakness, hypotonia and respiratory failure. "For example, mutations in MTM1, the founding member of this family, cause X-linked myotubular myopathy (XLMTM), a severe congenital muscular disorder, while mutations in MTMR2 and MTMR13 are associated with Charcot-Marie-Tooth disease." (PMID 23114011, 2012). "Mutations in MTMR family proteins are associated with the human neuromuscular disorders X-linked myotubular myopathy (myotubularin and MTMR1) and type 4B Charcot-Marie-Tooth neuropathy (MTMR2 and MTMR13)." (PMID 19325702, 2009).
acute myeloid leukemia (1 paper, 2023). Acute myeloid leukemia (AML) is a group of neoplasms arising from precursor cells committed to the myeloid cell-line differentiation. "On the other hand, the expression of MTMR2 was decreased in breast invasive carcinoma (BRCA), kidney chromophobe (KICH), acute myeloid leukemia (LAML), lung adenocarcinoma (LUAD), testicular germ cell tumors (TGCT), thyroid carcinoma (THCA), and uterine corpus endometrial carcinoma (UCEC)." (PMID 37907649, 2023).
Azoospermia (1 paper, 2008). Absence of any measurable level of sperm,whereby spermatozoa cannot be observed even after centrifugation of the semen pellet. "It has been proposed that Mtmr2-deleted mice show azoospermia because of a loss of cell adhesion between Sertoli and germ cells within the seminiferous epithelium." (PMID 18429927, 2008).
Charcot-Marie-Tooth disease, type (1 paper, 2024). "Finally, we have identified one infant with two variants in two different genes; one gene is MTMR2, causing Charcot-Marie-Tooth disease, type 4B1, and the other is aTCIRG1, causing osteopetrosis, autosomal recessive 135,36." (PMID 38600369, 2024).
embryonic carcinoma (1 paper, 2013). "To further test whether Gaa, Isl1, Kif1b, Mtmr2, Pcsk1n, and Snca, are regulated by Pax6, we performed co-transfection studies in cultured P19 embryonic carcinoma and αTN4-1 lens epithelial cells." (PMID 23342162, 2013).
gastric tumor (1 paper, 2025). "Myotubularin-related protein 2 (MTMR2) promotes gastric tumor progression by influencing the IFN-γ/STAT1 pathway." (PMID 40909948, 2025).
hepatocellular carcinoma (1 paper, 2023). A malignant tumor that arises from hepatocytes. "However, the various biological significances of MTMR2 in hepatocellular carcinoma (HCC) have not been systematically and comprehensively studied." (PMID 37907649, 2023).
lymph node metastasis (1 paper, 2019). "In this study, we demonstrated that MTMR2 highly expressed in GC tissues and its expression levels were significantly correlated with invasion depth and lymph node metastasis, as well as the outcome of the patients." (PMID 31113461, 2019).
metabolic syndrome (1 paper, 2020). A cluster of metabolic risk factors for CARDIOVASCULAR DISEASES and TYPE 2 DIABETES MELLITUS. "MTMR2 (myotubularin-related protein 2), belongs to the family of phosphoinositide phosphatases including several members mutated in neuromuscular diseases or those associated with metabolic syndrome, obesity, and cancer." (PMID 32143402, 2020).
PHARC syndrome (1 paper, 2021). Fiskerstrand type peripheral neuropathy is a slowly-progressive Refsum-like disorder associating signs of peripheral neuropathy with late-onset hearing loss, cataract and pigmentary retinopathy that become evident during the third decade of life. "Pigmentosus retinitis has been associated with PHARC syndrome and with ATP6 and MTMR2 gene variants." (PMID 34942918, 2021).
schizophrenia (1 paper, 2012). A major psychotic disorder characterized by abnormalities in the perception or expression of reality. "Interestingly, it has been shown that MTMR2 requires a Pleckstrin homology-GRAM domain for membrane association, and both MTMR2 and PLEK have been found here to be downregulated in the STG of schizophrenia patients." (PMID 22441714, 2012).
Sensorimotor neuropathy (1 paper, 2019). "Nevertheless, the age of onset was similar to previously reported cases and both children are suffering from muscle weakness, skeletal deformities, and early onset sensorimotor neuropathy, thus exhibiting typical symptoms of the MTMR2-related disease." (PMID 31680794, 2019).
cancer (7 papers, 2019 to 2025). A tumor composed of atypical neoplastic, often pleomorphic cells that invade other tissues. "Given its regulatory potential in cancer, MTMR2 is a promising biomarker; however, comprehensive research on the interaction mechanism between MTMR2 and macrophages is lacking." (PMID 40377731, 2025). "Additional genes upregulated in carcinoma patients as a result of CARD11 overexpression included MTMR2, EMB, EPHB6, and CPEB4, which are related to various cancer-related processes." (PMID 39408697, 2024). "Subsequently, we further assessed the relationship between MTMR2 and the survival of 33 cancer types through univariate Cox regression analysis." (PMID 37907649, 2023). "Abnormal expression of myotubularin-related protein 2 (MTMR2) has been identified in certain types of cancer, leading to varying effects on tumor genesis and progression." (PMID 37907649, 2023). "In this study, we analyzed the TCGA and GTEx databases and found that MTMR2 is significantly overexpressed in various cancer types, including HCC, and that increased expression of MTMR2 is associated with poor patient prognosis." (PMID 37907649, 2023). "The aberrant expression of myotubularin-related protein 2 (MTMR2) has been found in some cancers, but little is known about the roles and clinical relevance." (PMID 31113461, 2019). "We analyzed the mRNA expression of MTMR2 in pan-cancer using TCGA and GTEx datasets." (PMID 37907649, 2023). "MTMR2 exhibits high levels of expression across a wide range of cancer types, including HCC." (PMID 37907649, 2023). "Out of 33 types of cancer, the expression of MTMR2 differed significantly in 24 types." (PMID 37907649, 2023). "Consistent with our findings in in vitro studies, Ingenuity® Pathway Analysis (IPA®) showed that “migration of tumor cells”, “migration of cancer cells”, “cell movement of tumor cells” and “invasion of cells” ranked the top of “Diseases or Functions Annotation” related to MTMR2 depletion." (PMID 31113461, 2019). "This study explored the potential correlation between MTMR2 expression and the IC50 value of anti-cancer compounds." (PMID 37907649, 2023).
tumor (5 papers, 2010 to 2024). "We investigated the connection between MTMR2 and its expression, prognosis, clinical significance, methylation, genetic alterations, tumor microenvironment (TME), tumor mutation burden (TMB), and drug reactivity in HCC patients." (PMID 37907649, 2023). "We speculate that MTMR2 may promote immune escape and reduce the effectiveness of immunotherapy by increasing co-expression with immune checkpoints and inhibiting tumor cell mutation rates." (PMID 37907649, 2023). "In this study, we found that patients with high MTMR2 expression had higher stromal scores and tumor purity scores." (PMID 37907649, 2023). "Moreover, the intensity of MTMR2 staining in tumor tissues was increased with invasion depth." (PMID 31113461, 2019). "We analyzed the correlation between MTMR2 expression levels and clinical parameters, including AFP level, tumor stage, Histologic grade, TMN stage, tumor status, gender, and age." (PMID 37907649, 2023). "MTMR2 staining was low or absent in adjacent normal gastric mucosa, but was high in tumor tissues and metastatic lymph node." (PMID 31113461, 2019). "The expression levels of MTMR2 were significantly correlated with T stage (P = 0.004), N stage (P = 0.000), and TNM stage (P = 0.032), but not with the sex (P = 0.396), age (P = 0.313), tumor location (P = 0.524), histological grade (P = 0.172) or tumor size (P = 0.056)." (PMID 31113461, 2019).
peripheral neuropathy (4 papers, 2013 to 2024). A disorder affecting the peripheral nervous system. "Hypomorphic MTMR2 mutations are linked to Charcot–Marie–Tooth syndrome, an inherited form of peripheral neuropathy in humans." (PMID 31537807, 2019). "In this respect it is noteworthy that multiple Mtmr2 mutations – including those affecting its activity – have been implicated in Charcot-Marie-Tooth type 4B1 (CMT4B1) disease, a peripheral neuropathy characterized by abnormalities in myelination and nerve conduction." (PMID 29521261, 2018).
myopathy (3 papers, 2013 to 2023). A disease of the muscle in which the muscle fibers do not function properly. "Earlier studies have showing the rescue of MTM1 myopathy by MTMR2 overexpression, emphasize the importance of maintaining the phosphoinositides equilibrium and highlight a potential compensatory mechanism amongst members of this pathway." (PMID 31680794, 2019). "It was recently shown that MTMR2 can rescue MTM1-myopathy, with the short isoform being more effective." (PMID 31680794, 2019).
MTMR2 also shares sentences with these, for which no sentence is quoted: Charcot-Marie-Tooth Neuropathies (2 papers); neuromuscular disease (2); breast invasive carcinoma (1); centronuclear myopathy (1); demyelinating (1); facial nerve palsy (1); hereditary motor and sensory neuropathy (1); hereditary neuropathy with liability to pressure palsies (1); kidney chromophobe (1); lung adenocarcinoma (1); lung carcinoma (1); neurological disorders (1); NK/T cell lymphoma (1); Obesity (1); osteopetrosis (1); polyneuropathy (1); sarcopenia (1); sensory ataxia (1); Sézary syndrome (1); testicular germ cell tumor (1); thyroid carcinoma (1); uterine corpus endometrial carcinoma (1).